VWF (von Willebrand factor)
Diseases named in the same sentence as VWF in open-access papers (continued):
Sharing a sentence is not in itself a finding about the gene and the disease.
non-small cell lung carcinoma (3 papers, 2011 to 2022). A group of at least three distinct histological types of lung cancer, including non-small cell squamous cell carcinoma, adenocarcinoma, and large cell carcinoma. "In a study of the human tissue microenvironment in non-small cell lung cancer demonstrated that the disintegrin and metalloproteinase 28 (ADAM28) can promote metastasis by binding to and cleaving vWF in carcinoma cells." (PMID 25886574, 2015).
pterygium (3 papers, 2016 to 2021). A wedge-shaped fibrovascular lesion arising from the bulbar conjunctiva and extending to the cornea. "Compared with the conjunctiva, several key factors related to angiogenesis, such as PECAM1, CD34, VWF, and ENG, were highly expressed in the pterygium." (PMID 33790949, 2021). "Among the top 20 connective genes from PPI network, FN1, VWF, and IGFBP3 have been reported and expressed disorderly in pterygium." (PMID 31341891, 2019). "Additionally, CD34, VWF, and ENG, endothelial cell surface markers, and their positive microvascular counts were markedly higher in pterygium than those in conjunctival tissue." (PMID 33790949, 2021).
purpura (3 papers, 2018 to 2025). A small blood vessel hemorrhage into the skin and/or mucous membranes. "Thus, we considered vWF disease, platelet dysfunction, and vascular disease to have caused purpura." (PMID 29690915, 2018). "Other aptamers, like ARC1779, targeting activated von Willebrand Factor (vWF), have verified efficacy against purpura and thrombotic thrombocytopenic disease." (PMID 30682091, 2019).
renal carcinoma (3 papers, 2021). A carcinoma arising from the epithelium of the renal parenchyma or the renal pelvis. "In the present study, apart from SKCM, kidney renal papillary cell carcinoma exhibited CDK2, CDK4, KIT, and VWF Cox coefficient values of > 0, indicating that the high expression of these four key genes is a risk factor for patients with renal carcinoma." (PMID 34582363, 2021). "The results showed that EIF4EBP1, FOXM1, PLG, and VWF were highly expressed in renal carcinoma compared with normal renal tissue, and ADAM8, CGN, G6PC, ITIH4, and MMP3 were low in expression in renal carcinoma compared with normal renal tissue." (PMID 33968297, 2021).
septic arthritis (3 papers, 2020 to 2022). "vWF-deficient mice were more susceptible to bone damage in septic arthritis, especially when the Δvwb strain was used." (PMID 33203754, 2020). "Four isogenic S. aureus strains differing in expression of coagulases (wild-type [WT] Newman, Δcoa, Δvwb, and Δcoa Δvwb) were used to induce septic arthritis in both wild-type and von Willebrand factor (vWF)-deficient mice." (PMID 33203754, 2020). "Another unexpected finding was that the characteristics of septic arthritis are somehow different in the vWF-deficient mice compared to WT mice, as there was significantly deeper joint involvement in the vWF knockout mouse than WT controls." (PMID 33203754, 2020). "We speculate that bacterial vascular adhesion mediated by a ClfA-vWbp-vWF complex might be one of the explanations for the pathogenic role of ClfA in septic arthritis." (PMID 33203754, 2020). "The increased risk for septic arthritis in RA patients might be partially explained by endothelial injury and accumulation of hyperreactive vWF on the endothelium surface of inflamed joints." (PMID 33203754, 2020). "The question then arises, is there any better way to confirm the relevance of vWbp-vWF interaction in septic arthritis?" (PMID 33203754, 2020). "Of note, protein A, also possessing binding capacity to vWF, has also been shown to be a virulence factor in S. aureus septic arthritis." (PMID 33203754, 2020). "It is clear that vWF-deficient mice are more susceptible to the bone damages in S. aureus septic arthritis than the wild-type mice, especially in the bacteria lacking vWbp expression." (PMID 33203754, 2020). "Thus, the vWF-binding protein/vWF-mediated bacteria joint-invading capacity might be a universal disease mechanism for hematogenous septic arthritis." (PMID 33203754, 2020). "The protective role of vWF in septic arthritis might be explained by the link between vWF and inflammation, as vWF is known to possess the capacity to attract the leukocytes by either direct binding or recruitment of platelets, which, in turn, recruit leukocytes." (PMID 33203754, 2020). "However, under conditions of high shear stress, protein A does not promote bacterial adherence to vWF, which rules out the possibility of bacterial vascular adhesion mediated by protein A in septic arthritis." (PMID 33203754, 2020).
Shock (3 papers, 2017 to 2025). The state in which profound and widespread reduction of effective tissue perfusion leads first to reversible, and then if prolonged, to irreversible cellular injury. "A high vWF:Ag/ADAMTS13 ratio has been associated previously with the development of TMA, higher severity of shock, degree of organ failure, and worse outcomes in patients with septic shock." (PMID 32122366, 2020).
staphylococcus aureus infection (3 papers, 2019 to 2024). An infectious process in which the bacteria Staphylococcus aureus is present. "Staphylococcus aureus infection has been shown to be associated with increased levels of neutrophil extracellular traps (NETs) and von Willebrand factor (VWF) and decreased ADAMTS13 activity." (PMID 39408067, 2024).
systemic vasculitis (3 papers, 2009 to 2021). "Serological markers such as CRP and von Willebrand factor are possible indicators of endothelial injury in systemic vasculitis but may not reflect the activity in isolated organ disease." (PMID 21672251, 2011).
transient ischemic attack (3 papers, 2015 to 2021). A brief attack (from a few minutes to an hour) of cerebral dysfunction of vascular origin, with no persistent neurological deficit. "Blood samples were obtained from 33 patients with acute stroke or transient ischemic attack to measure inhibition of VWF activity and VWF-dependent platelet function." (PMID 33542410, 2021).
uremia (3 papers, 2025). A clinical syndrome associated with the retention of renal waste products or uremic toxins in the blood. "Simultaneously, uremia-induced endothelial injury disrupts von Willebrand factor multimer distribution and nitric oxide signaling, further weakening primary hemostasis." (PMID 41464761, 2025). "Uremia in ESRD impairs platelet aggregation and adhesion by reducing platelet glycoprotein expression and inhibiting von Willebrand factor activity, leading to a uremic bleeding diathesis." (PMID 39791018, 2025).
valvular heart disease (3 papers, 2020 to 2022). "Heyde syndrome comprises the combination of AvWS, valvular heart disease and bleeding tendency – in particular gastrointestinal bleeding‐8 as a result of an increased clearance of vWF related to shear‐induced proteolysis of high‐molecular‐weight vWF multimers when passing the abnormal valve." (PMID 33372698, 2021). "As characterized by Heyde syndrome AvWS, valvular heart disease and bleeding tendency result in an increased clearance of vWF due to shear stress leading to a proteolysis of HMWM vWF during the passage of the abnormal heart valve." (PMID 33372698, 2021).
vivax malaria (3 papers, 2011 to 2015). "Studies performed in both falciparum and vivax malaria demonstrate an inverse association between the circulating platelet count and plasma concentrations and activity of vWF." (PMID 25907925, 2015).
von Willebrand disease type 3 (3 papers, 2011 to 2021). "For instance, BOEC derived from patients with type 3 von Willebrand disease (a congenital deficiency in endothelial-derived VWF expression) appeared to be dysfunctional in the release of large VWF multimers that capture platelets under flow conditions." (PMID 31744132, 2019). "We describe the case of a patient with von Willebrand disease type 3 with a large iliopsoas hematoma who was treated with a von Willebrand factor concentrate (Humate-P)." (PMID 21722393, 2011).
acute aortic dissection (2 papers, 2020 to 2022). "Zindovic and colleagues reported that in acute aortic dissection, VWF activity just before the end of surgery was unchanged compared to preoperative levels." (PMID 32648135, 2020). "Nine proteins (Lumican, FGL1, PI16, MMP9, FBN1, MMP2, VWF, MMRN1, and PF4) related to the pathogenesis of aortic dissection were identified by David /Ease and String techniques as candidate biomarkers for verification test." (PMID 35910577, 2022).
acute pancreatitis (2 papers, 2015 to 2020). An acute inflammatory process that leads to necrosis of the pancreatic parenchyma. "Proinflammatory mediators released during the systemic inflammatory response seen in acute pancreatitis can promote VWF activity and inhibit ADAMTS13 activity." (PMID 32642381, 2020).
adenoma (2 papers, 2012 to 2014). A neoplasm arising from the epithelium. "Moreover, the densities of Von Willebrand factor (vWF)-positive vessels were significantly greater in adenoma and adenocarcinoma than in normal tissues in human specimens." (PMID 24885408, 2014).
arteriosclerosis (2 papers, 2018 to 2022). A vascular disorder characterized by thickening and hardening of the walls of the arteries. "Arteriosclerosis is a localized inflammatory process in which increased amounts of ultra-large vWF strings are released from Weibel–Palade bodies under shear stress and attached to the inflamed endothelial surface." (PMID 29847840, 2018).
astrocytomas (2 papers, 2016 to 2022). "Previous studies accordingly reported a direct relationship between VWF levels in microvessels and different grades of astrocytomas." (PMID 35052804, 2022).
autoimmune hepatitis (2 papers, 2019 to 2025). Hepatitis caused by autoantibodies. "Meanwhile, ROC analysis (AUC: 0.880; 95% CI 0.825–0.934) showed that vWF could be a better indicator of AIC, and was also a better dynamic observation index in different stages of autoimmune liver disease." (PMID 29999587, 2019).
Behçet’s Disease (2 papers, 2021 to 2025). "Moreover, Von Willebrand Factor, a marker for endothelial cell activation and a mediator for platelet activation, is observed to be increased in Behcet disease and ischemic retinal vasculitis." (PMID 38983969, 2021).
Brain atrophy (2 papers, 2023 to 2025). Partial or complete wasting (loss) of brain tissue that was once present. "In old rats, the vWF-positive microvessel density in the brain was reduced to 27.8% of young animals, and the relative brain weight decreased, meaning brain atrophy." (PMID 38067139, 2023). "This could suggest that the effects of VWF on brain atrophy may be region-specific, potentially reflecting the distinct vascular supply and functional roles of different brain regions." (PMID 40969184, 2025).
carcinoma in situ (2 papers, 2002 to 2022). "Compared to normal lobules, pure ductal carcinoma in situ exhibited a greater density of CD34+ and CD31+ vessels but a decrease in those that were immunopositive for vWF, indicating a difference in phenotype and in density." (PMID 11953822, 2002).
cardiac arrest (2 papers, 2019 to 2024). Cessation of breathing and/or cardiac function. "ECMO treatment in patients with out-of-hospital cardiac arrest resulted in the loss of large vWF multimers and decreased vWF activity." (PMID 38822325, 2024). "In the present study, endothelial cell stimulation by cardiac arrest and resuscitation induced the release of vWF and increased vWF: Ag levels." (PMID 38822325, 2024).
cardiac hypertrophy (2 papers, 2016 to 2020). "Specifically, markers of non-cardiac differentiation, such as those for vascular endothelium (VWF) and non-cardiac muscle (CDH6, CNN2 and MYLK) were downregulated, while genes encoding for cardiac hypertrophy (IGF1R) and calcium handling (CAMK2B) were upregulated." (PMID 26785135, 2016).
cavernomas (2 papers, 2021 to 2022). "Interestingly, vWF accumulates in the lumen of human cavernomas, and in vitro models of CCM show that vWF increases in endothelial cells and forms vWF-strings in the absence of CCM1 or CCM3." (PMID 36293431, 2022).
cerebral cavernous malformation (2 papers, 2017 to 2021). A disorder characterized by malformations in the structure of the capillaries in the brain. "A strong signal for the local subnetwork around Von Willebrand Factor (VWF), a gene which showed no change on the mRNA level, was identified by LEAN in transcriptome data in the context of the genetic disease Cerebral Cavernous Malformations (CCM)." (PMID 27797778, 2017).
cerebral microbleeds (2 papers, 2019 to 2021). Cerebral microbleeds are a group of pathological processes affecting the small arteries, arterioles, capillaries and venules of the brain, as detected by brain imaging techniques. "Interestingly, decreased ADAMTS13, which exerts an inhibitory function on vWF activity, was detected in MS patients and in particular in those with cerebral microbleeds." (PMID 31068896, 2019).
cerebral thrombosis (2 papers, 2019 to 2021). "NETs are also an important component of cerebral thrombosis, are cytotoxic to endothelial cells, and together with von Willebrand factor (VWF), promote the hypercoagulable state." (PMID 34926629, 2021).
cervical cancer (2 papers, 2006 to 2023). A primary or metastatic malignant neoplasm involving the cervix. "Elevated VWF plasma levels have been found in node positive cervical cancer patients, consistent with our results." (PMID 17054779, 2006).
chronic hepatitis (2 papers, 2019 to 2022). An active inflammatory process affecting the liver for more than six months. "VWF was reported to be associated with the progression of LC in chronic hepatitis and was negatively correlated with platelet count, prothrombin time, and albumin level." (PMID 36002595, 2022).
chronic liver failure (2 papers, 2023). Liver failure that develops slowly and gradually for some time, possibly for years, often as the result of cirrhosis, or malnutrition. "The chronic liver failure consortium (CLIF-C) ACLF score, MELD score, VWF:Ag level, and VWF:Ag/ADAMTS13:AC level in the survival subgroup of the post-ACLF group were lower than those of the mortality subgroup (p < 0.05 for all)." (PMID 36829443, 2023).
chronic thromboembolic pulmonary hypertension (2 papers, 2023 to 2025). Chronic thromboembolic pulmonary hypertension (CTEPH) is characterized by the persistence of thromboemboli in the form of organized tissue obstructing the pulmonary arteries. "Elevated levels of vWF were found in IPAH and in patients with chronic thromboembolic pulmonary hypertension (CTEPH), as well as lcSSc patients with an increased risk for PH." (PMID 36835590, 2023).
co-infection (2 papers, 2021 to 2025). "Furthermore, considering the fact that VWF is a mediator for many other pathogens, such as S. aureus dissemination, it will be interesting and important to know whether the interaction with E. hellem interferes or facilitates co-infection with other pathogens." (PMID 34095003, 2021).
congenital heart disease (2 papers, 2016 to 2022). A heart disease that is present at birth. "Recent studies show that treatment algorithms including supplementation of VWF concentrate may reduce perioperative blood loss in children with congenital heart disease." (PMID 36568413, 2022).
cutaneous melanoma (2 papers, 2017 to 2025). A primary melanoma arising from atypical melanocytes in the skin. "Our results demonstrated that mutations in genes encodingFVIII,VWF, andADAMTS13were reported in 92 of 126 cancer genomic studies, and high mutation rates in these three genes were observed in patients with cutaneous melanoma from three independent studies." (PMID 29152610, 2017). "To investigate the possible underlying mechanism of the protective role ofFVIIImutations in patients with cutaneous melanoma, we tested the effect of mutations inFVIII,VWF, andADAMTS13on mRNA expression based on the RNA-Seq data." (PMID 29152610, 2017). "This article takes advantage of the recent whole exome sequence (WES) datasets, mRNA expression (RNA-seq) data, and bioinformatics tools to determine the prognostic value of somatic mutations inFVIII,VWF, andADAMTS13in cutaneous melanoma." (PMID 29152610, 2017). "In addition, the spatial transcription data on SpatialDB showed that RAB5B spatially overlapped with endothelial cell markers PECAM1 and VWF in BCC cancer tissues and M2 macrophage markers CD68 and CD163 in skin melanoma tissues." (PMID 40842984, 2025).
cyst (2 papers, 2005 to 2025). A sac-like closed membranous structure that may be empty or contain fluid or amorphous material. "In patients with VWD, the absence or deficiency of von Willebrand factor prevents adequate spontaneous hemostasis, allowing continued bleeding after cyst rupture and resulting in significant hemoperitoneum that may lead to hemodynamic instability." (PMID 41541967, 2025).
Ductal carcinoma in situ (2 papers, 2002 to 2020). "Ductal carcinoma in situ associated with invasive carcinoma showed a profile of vascular immunostaining similar to that of pure ductal carcinoma in situ but there were significantly greater numbers of CD34+ and CD141+ vessels and fewer staining for vWF." (PMID 11953822, 2002).
endometriosis of the ovary (2 papers, 2016 to 2023). "In summary, the evidence suggests that ADAMTS13 may have a negative causal relationship with endometriosis of the ovary, pelvic peritoneum, and uterus, while vWF may have a positive causal relationship with endometriosis of the ovary and pelvic peritoneum." (PMID 37226166, 2023). "To confirm neo-vascularisation, we performed immunofluorescence study with anti-von Willebrand factor (VWF) antibody in the early and late stages of ovarian endometriosis." (PMID 27695098, 2016).
escherichia coli infection (2 papers, 2019 to 2021). Infection with the organism Escherichia Coli. "During acute infections, such as Escherichia coli infection may induce the haemolytic uremic syndrome, triggering the formation of microvascular thrombi mediated by Von Willebrand Factor (VWF)." (PMID 34095003, 2021).
head and neck cancer (2 papers, 2016 to 2021). A primary or metastatic malignant neoplasm affecting the head and neck. "Despite these constraints and differences in study design compared with our work, we highlight that both this study and ours identified upregulated expression of von Willebrand factor and integrin beta-1 in EVs from patients with head and neck cancer." (PMID 34571828, 2021). "These include serum amyloid A-4, complement C1q subcomponent subunit C, and von Willebrand factor, all of which have been identified by previous EV head and neck cancer studies." (PMID 34571828, 2021).
hepatitis C (2 papers, 2021 to 2022). "Some previous studies reported that interferon and direct acting antivirals (DAAs) helped in recovery from the imbalance between ADAMTS13 enzyme and VWF substrate and high Et levels in patients with LC and hepatitis C." (PMID 35407443, 2022).
human papillomavirus infection (2 papers, 2021 to 2025). "From KEGG, circRNAs are enriched in PI3K/AKT, human papillomavirus infection (HPI), and focal adhesion (FA) pathways, and VWF was involved in major pathways." (PMID 34527744, 2021). "KEGG signaling pathway analysis showed that circRNAs are enriched in PI3K/AKT, human papillomavirus infection (HPI), focal adhesion (FA), and other seven pathways, and VWF and COL6A3 were involved in 4/7 pathways." (PMID 34527744, 2021).
Hypernatremia (2 papers, 2022 to 2025). An abnormally increased sodium concentration in the blood. "Second, hypernatremia caused by diarrhea stimulates the production of the clotting initiator, von Willebrand factor, in endothelial cells and promotes thrombogenesis." (PMID 35268431, 2022).